ZEB1 (zinc finger E-box binding homeobox 1)
Diseases named in the same sentence as ZEB1 in open-access papers (continued):
Sharing a sentence is not in itself a finding about the gene and the disease.
prostate carcinoma (continued). "MiR-205, which is induced by p63, was reported to inhibit EMT by targeting ZEB1 and ZEB2 in breast cancer and prostate cancer." (PMID 24598126, 2014). "In prostatic cancer cells Byles and colleagues observed Sirt1 to modulate EMT upon EGF signalling via the induction of the transcription factor ZEB1." (PMID 24088390, 2013). "We showed that interactions between epithelial prostate cancer cells with M2-type macrophages resulted in EMT, as well as the upregulation of the EMT-inducing TF ZEB1." (PMID 24124593, 2013). "Similar to our finding in prostate cancer cells, expression of OVOLs induced MET and high ESRP expression, while significantly decreasing ZEB1 expression." (PMID 24124593, 2013). "Other experiments in prostate cancer cells induced to undergo EMT led to similar findings concerning the regulation of the OVOL and ZEB1 TFs." (PMID 24124593, 2013). "Several of the differentially expressed genes are known to play a critical role in prostate cancer, such as APC, MAPK7, or ZEB1." (PMID 22568834, 2012). "Our preliminary results showing that ZEB1 mRNA levels increase in response to androgen treatment in the 22RV1 and PC3/AR prostate cancer cell lines have been published." (PMID 22190929, 2011). "Furthermore, the KM plotter and GEPIA results demonstrated that when prostate cancer progresses, there are changes in the expression of CDH1, CDH2, VIM, SNAI1, ZEB1, and ZEB2." (PMID 40693059, 2025). "ZEB1 binds to the LAMC2 promoter and represses its expression in prostate cancer cells." (PMID 38508310, 2024). "With regards to clinical relevance, ZEB1 expression increases progressively through the different stages of cancer progression, e.g., ZEB1 expression dramatically increases in advanced castration-resistant prostate cancer (CRPC) and PCa metastasis compared to clinically localized prostate cancer." (PMID 32266287, 2020). "During the examination of many sections of human prostate cancer samples, we infrequently found cancer tissues (Gleason score: 3 + 3 or 3 + 4, n = 4) with remaining CK14+ basal cells, in which Zeb1 positive staining could be found." (PMID 32024836, 2020). "Also, miR-205 upregulation enhances radiation response in a prostate cancer cell line as well as in xenograft models by impairment of DDR and DNA repair as a consequence of ZEB1 inhibition." (PMID 32266287, 2020). "Likewise, SIRT1 is recruited to the promoter of E-cadherin and acts as a co-suppressor with ZEB1 to synergistically inhibit E-cadherin transcription, thus promoting EMT in prostate cancer." (PMID 31068761, 2019). "Furthermore, inhibition of GPC-1 decreased several markers of prostate cancer aggression, such as MMP-9, E-Cadherin (E-Cad), N-Cadherin (N-Cad), CXCR4, vimentin (VIM), Zeb1 and Zeb238–40, as determined using qRT-PCR." (PMID 31391540, 2019). "Consistent with this hypothesis, histone deacetylase inhibitors increased EMT markers, including ZEB1, TWIST1, and vimentin in prostate cancer cells." (PMID 31101737, 2019). "Furthermore, Zeb1 can directly regulate miR-375 expression by directly binding to its promoter, leading to transcriptional repression and thus activation of EMT in prostate cancer." (PMID 29843425, 2018). "In this study, we investigated for the first time the role of both ZEB1 and ZEB2 in docetaxel‐resistant prostate cancer and provide strong evidence for ZEB1, through its transcriptional repression of E‐cadherin to be a driver of both EMT and docetaxel resistance." (PMID 28133913, 2017). "In order to investigate the clinical relevance of ZEB1‐mediated EMT in response to docetaxel therapy, we performed IHC analysis of ZEB1 tumour expression in 27 patients with prostate cancer; 14 of whom were treated with docetaxel prior to radical prostatectomy." (PMID 28133913, 2017).
prostate carcinoma (continued). "We found three groups of genes in the EMT differentially expressed list: a) known EMT genes (e.g. CDH1, ZEB1, TGFB, CDH2, VIM, TIMP1), b) EMT genes previously unknown in prostate cancer (LSR, S100A14, DPYSL3) and c) novel EMT genes (including C1orf116)." (PMID 28651527, 2017). "Thus, in order to identify the protein mediators downstream to PlexinD1, we analyzed the expression of EMT transcription factors Snail, Slug, Twist, Zeb1 and Zeb2 in PC3 prostate cancer cells." (PMID 27749937, 2016). "Remarkably silibinin was able to reverse epithelial-to-mesenchymal transition (EMT) in metastatic prostate cancer cells by down-regulating the two major EMT regulators, ZEB1 and SLUG transcription factors, while its role in inhibiting STAT3 signaling is well documented." (PMID 28042859, 2016). "In human prostate cancer cells, IGF-1 upregulates ZEB1 and drives EMT." (PMID 25436001, 2015). "Moreover, miR-200 regulated PDGF-D-mediated EMT partly through down-regulation of ZEB1, ZEB2 and Snail, and up-regulation of E-cadherin in prostate cancer cells." (PMID 24158561, 2013). "Given evidence of reciprocal feedback loops between ZEB1/2 and miR-200 family members in EMT-MET transformations, we explored the contribution of miR-200s as potential inducers of epithelial differentiation in the breast and prostate cancer models." (PMID 24124593, 2013). "Functional silencing of IGFBP3 in prostate cancer epithelial cells resulted in increased E-cadherin, while neither of the transcriptional repressors, Snail or ZEB1 mRNA expression was significantly affected (by IGFBP3 knockdown) begging the question as to its role in EMT-MET cycling." (PMID 29108245, 2017). "In contrast, androgens do not induce ZEB1 in an AR-positive prostate cancer cell line." (PMID 26797644, 2016). "Interestingly, we observed an upregulation of ZEB1, NOG and slightly of FST in a docetaxel resistant subclone of DU145 prostate cancer cells, supporting our data of correlated ZEB1 and BMP-inhibitor expression, here during ZEB1 mediated induction of chemoresistance." (PMID 25973542, 2015). "Interestingly, a well-known gene fusion in prostate cancer that is produced by deletion of a 3-mega base region between ERG and TMPRSS2 (also reviewed in [Parker 2014 Journal of Pathology]) has also been found to upregulate ZEB1 and ZEB2 expression." (PMID 24598126, 2014). "The negative correlation between expression of the OVOLs and ZEB1 in multiple cancers indicates that the function of the OVOLs may not be restricted to prostate cancer." (PMID 24124593, 2013). "Treatment of the PC-3/AR prostate cancer cell line, which overexpresses AR, with dihydrotestosterone (DHT) induced endogenous ZEB1 mRNA and protein, confirming our observations that androgen increases ZEB1 mRNA and showing for the first time that this is reflected in ZEB1 protein levels." (PMID 22190929, 2011). "Intriguingly, Zeb1+ CK8+ luminal cells were barely detected in non-BPH but could be observed occasionally in BPH specimens and more frequently in prostate cancer specimens." (PMID 32024836, 2020).
ovarian carcinoma (147 papers, 2010 to 2026). A malignant neoplasm originating from the surface ovarian epithelium. "While some of these circRNAs, such as hsa_circ_0007883, have been previously linked to cancer progression (e.g., ZEB1 regulation in ovarian cancer), their specific roles in lead-induced neurotoxicity and mitochondrial function require further elucidation." (PMID 40725099, 2025). "One group showed that ZEB1 promoted the transcription of circANKRD17 and caused the progression of ovarian cancer." (PMID 38152652, 2023). "This is consistent with other studies which show that high protein levels of ZEB1 are associated with poor progression-free and overall survival in ovarian cancer." (PMID 35794446, 2022). "As miR-200 regulation is critical for the key EMT-TF ZEB1 expression, we next examined the underlying mechanism driving ZEB1 expression in ovarian cancer." (PMID 33188287, 2020). "In the current study, we linked miR-150 to its target gene ZEB1, and demonstrated their involvements in regulating malignant phenotypes of ovarian cancer cells." (PMID 25090005, 2014). "ZEB1 may be a useful as marker of progression, invasion and metastasis in ovarian cancer which is associated with poor overall survival." (PMID 35794446, 2022). "Among the cytokines most highly regulated by the ET-1/ETAR-activated GSDME/ZEB1 signaling network, we noted interleukin (IL)-6, a gatekeeper of cancer cell/TME communication implicated in ovarian cancer growth, metastasis and immune evasion." (PMID 41545335, 2026). "OC-MQs increased mesenchymal markers’ expression, including SNAI1, CDH2, FN, VIM, and ZEB1, in ovarian cancer cells." (PMID 39937005, 2025). "CCAT1 silencing decreases the migration and invasion of ovarian cancer cells via the CCAT1/miR-130b/ZEB1 axis." (PMID 39967908, 2025). "Key findings include the identification of core EMT regulators, such as TWIST1, SNAIL, and ZEB1, which are upregulated in both ovarian cancer and GBM, promoting mesenchymal phenotypes and metastasis." (PMID 39936963, 2025). "The identification of this positive feedback loop involving SRSF9, USP22, and ZEB1 offers new insights into the molecular mechanisms driving ovarian cancer progression." (PMID 39530604, 2024). "Molecular investigations have revealed that subtypes of TGF-β (TGF-β1, TGF-β2, and TGF-β3) upregulate ZEB1 expression, promoting ovarian cancer peritoneal metastasis." (PMID 39247601, 2024). "Tissue transglutaminase (TG2) activates NF-κB, which in turn activates ZEB1 to promote ovarian cancer peritoneal metastasis." (PMID 39247601, 2024). "For example, inhibitors of EMT‐related protein ZEB1 have shown therapeutic potential in ovarian carcinoma in vitro." (PMID 38650367, 2024). "In ovarian cancer, sorcin was found to drive malignant progression via the Smad4/ZEB1/miR-142-5p axis." (PMID 39199583, 2024). "The effects of downregulated lncRNA HOTAIR on EOC invasiveness and tumorigenicity in nude mice, along with TGF- β1 and ZEB1 in epithelial ovarian cancer cells, need to be investigated in further research." (PMID 38070058, 2023). "Our research elucidates the expression relationship between lncRNA HOTAIR, TGF-β1, ZEB1, and E-cadherin in epithelial ovarian cancer." (PMID 38070058, 2023). "In brief, in this research, lncRNA HOTAIR downregulation caused a decrease in zeb1 and TGF-β1 but an increase in E-cadherin in epithelial ovarian cancer SKOV3 cells." (PMID 38070058, 2023). "In summary, downregulated lncRNA HOTAIR in EOC SKOV3 cells transfected with shHOTAIR can inhibit TGF-β1, reduce ZEB1, increase E-cadherin, and significantly reduce the invasiveness and tumorigenicity of ovarian epithelial cancer SKOV3 cells." (PMID 38070058, 2023). "In our study, down-regulation of the lncRNA HOTAIR in SKOV3 epithelial ovarian cancer cells reduced the expression of zeb1 and TGF-β1." (PMID 38070058, 2023).
ovarian carcinoma (continued). "Silencing of ZEB1 downregulated the expression of circANKRD17, while overexpression of ZEB1 upregulated circANKRD17 expression level in ovarian cancer cells." (PMID 38152652, 2023). "miR-200 family members can repress ZEB1 expression and thus inhibit the capacity of ovarian cancer cells to undergo migration and invasion." (PMID 36512117, 2022). "ZEB1 knockdown has been shown to reverse cisplatin resistance in SKOV3/CDDP ovarian carcinoma and SGC7901/DDP gastric carcinoma cells." (PMID 35794446, 2022). "NEAT1 has been discovered to be a tumor promoter in ovarian cancer by sponging miR-194 to regulate ZEB1 expression." (PMID 34991683, 2022). "Increased protein expression of ZEB1 was observed in two paclitaxel-resistant ovarian-cancer cell lines OV3R-PTX and SK3R-PTX." (PMID 35794446, 2022). "For example, ZEB1 is involved in PCa resistance to docetaxel and, in ovarian cancer, resistance to cisplatin." (PMID 35682554, 2022). "Emodin, for example, inhibits ovarian cancer SKOV3 cell invasion by inhibiting EMT by regulating the GSK-3β/β-catenin/ZEB1 signaling pathway." (PMID 35035481, 2022). "ZEB1 was identified as differentially expressed in IGROVCDDP by microarray, and has been previously associated with EMT in ovarian-cancer cells." (PMID 35794446, 2022). "LncRNA PTAR promotes the EMT and metastasis in ovarian cancer by acting as a ceRNA to targeting miR-101-3p/ZEB1 axis." (PMID 33407499, 2021). "The presence of overexpressing miR-150 lessens the invasive and metastatic activity of ovarian cancer cells by targeting the expression of Zinc Finger E-Box Binding Homeobox 1 (ZEB1) protein." (PMID 33805515, 2021). "For example, LncRNA NEAT1 contributes to paclitaxel resistance of ovarian cancer cells by regulating ZEB1 expression via miR-194." (PMID 32296457, 2020). "Meanwhile, MMP9 secreted from TAMs containing ZEB1 was shown to upregulate CCL2 expression in ovarian cancer cells." (PMID 32283687, 2020). "In ovarian cancer, members of the miR-200 family have been implicated with EMT in which ZEB1 and ZEB2 were their targets." (PMID 32316405, 2020). "Since low levels of miR-200c are associated with chemoresistance, high ZEB1 levels, and EMT in advanced breast and ovarian cancer, restoration of its expression is considered as a promising therapeutic approach to overcome limited therapeutic response." (PMID 32266287, 2020). "In ovarian cancer, NEAT1 is elevated and increases paclitaxel resistance of ovarian cancer via upregulating zinc finger E-box-binding homeobox 1 (ZEB1) expression by sponging miR-194." (PMID 33292252, 2020). "For instance, a newly identified lncRNA called PTAR, the expression of which correlates significantly with tumor subtype, promotes the epithelial-mesenchymal transition (EMT) and metastasis in ovarian cancer via the miR-101-3p/ZEB1 pathway." (PMID 32962742, 2020). "Future combination therapy preclinical studies should be conducted to design successful trials reflecting the full therapeutic potential of ET-1R antagonists in ovarian cancer treatment, targeting the miR-200/ZEB1 circuit." (PMID 33188287, 2020). "Collectively, these findings demonstrate that miR-200b/c are involved in the regulation of ETAR and ZEB1 expression in ovarian cancer cells." (PMID 33188287, 2020). "Collectively, these findings highlight the reciprocal network that integrates ETAR and ZEB1 axes with the miR-200b/c regulatory circuit to favour metastatic progression in ovarian cancer." (PMID 33188287, 2020). "Using different approaches, we demonstrate that the ETAR-miR-200b/c-ZEB1 integrated circuit acts as a key node to confer aggressive traits to ovarian cancer cells fostering tumor progression." (PMID 33188287, 2020).
ovarian carcinoma (continued). "The analysis of ETAR and ZEB1 protein expression in a panel of ovarian cancer cells revealed their positive correlation." (PMID 33188287, 2020). "Expression of ZEB1 in macrophages polarized them to become an F4/80low pro-tumor phenotype and contributed to chemoresistance in mice of ovarian cancer." (PMID 32283687, 2020). "To evaluate the impact of the ETAR-miR-200b/c-ZEB1 interplay on metastatic progression in vivo, we performed experiments using different ovarian cancer xenograft models." (PMID 33188287, 2020). "LncRNA NEAT1 suppresses the inhibitory effect of miR-194 on ZEB1 to induce the resistance of ovarian cancer cells into PTX chemotherapy." (PMID 32664703, 2020). "Altogether, these results highlight a potential interplay between ETAR and ZEB1 in the control of clinical outcome of ovarian cancer." (PMID 33188287, 2020). "Further, loss of miR-200c led to the induction of Snail and ZEB1, activation of EMT, and abnormal expression of beta-tubulin III (TUBB3), leading to paclitaxel resistance in ovarian cancer cell models." (PMID 32266287, 2020). "Forced expression of miR-200 family members represses ZEB1 expression and inhibits the capacity of ovarian cancer cells to undergo migration and invasion, implicating ZEB1 as a miR-200 target." (PMID 33188287, 2020). "In the future, well-designed cohort studies with a larger sample size and more complete follow-up data, as well as in-depth molecular mechanism researches are needed to elucidate the role of CD44 and ZEB1 in the chemoresistance of ovarian cancer." (PMID 31497537, 2019). "Our study has proposed a new mechanism by which CD44 induces the EMT progress via ZEB1 and Snail in ovarian cancer." (PMID 31497537, 2019). "miR-1236-3p can suppress ovarian cancer metastasis by binding to the 3’ untranslated region of zinc-finger E-box binding homeobox 1 (ZEB1) mRNA, and downregulate ZEB1 gene expression." (PMID 31480283, 2019). "The intermediate E ovarian carcinoma cell lines exhibit significantly higher levels of SNAI1 mRNA and lower levels of ZEB1/2 mRNAs relative to the intermediate M ovarian carcinoma cell lines." (PMID 31121840, 2019). "Ji An, etc reported that lncRNA NEAT1 affected paclitaxel resistance in ovarian cancer by recruiting miR − 194 to target ZEB1 and then regulating P-gp and GST." (PMID 31391118, 2019). "Several EMT drivers, such as Snail, Slug and TCF8/ZEB1, have been closely associated with recurrence and survival in patients with breast, colorectal and ovarian cancer, indicating that the EMT process leads to poor clinical outcomes." (PMID 30971296, 2019). "In recent study, ZEB1 can regulate therapy resistance in lung adenocarcinoma, hepatocarcinoma and ovarian cancer." (PMID 30992025, 2019). "Hsa-miR-150 has been reported to be down-regulated in human epithelial ovarian cancer and to inhibit cell invasion and metastasis through inhibiting transcriptional repressor ZEB1." (PMID 29755664, 2018). "MiR-150-5p was revealed to target ZEB1 in various cancers such colon cancer, esophageal squamous cancer and ovarian cancer, and ZFAS1 was demonstrated to sequestrate miR-150-5p and exerted its pro-metastatic activity in hepatocellular cancer." (PMID 28697764, 2017). "And lastly, it has been shown for the ovarian cancer cell line SKOV-3 that inhibition of ZEB1, which is predicted as a master regulator, hampers migration in vivo and tumor growth in vitro when xenografted in mice." (PMID 28854983, 2017). "Downregulation of miR-200 in mesenchymal cells of uterine carcinosarcomas and ovarian cancer cells increases the expression of Zeb1/2." (PMID 26356073, 2015). "In ovarian cancer cells, overexpression of Zeb1 induced mesenchymal markers TSHZ1 and FBN1, thus promoting EMT." (PMID 26356073, 2015). "Overall our results demonstrated that both ZEB2 and ZEB1 contributed to the migratory and anchorage-independent cell growth abilities in Hey ovarian cancer cell line." (PMID 26136338, 2015).